SMAD2 (SMAD family member 2)
Diseases named in the same sentence as SMAD2 in open-access papers (continued):
Sharing a sentence is not in itself a finding about the gene and the disease.
cancer (continued). "We identified an increase in phosphorylation of P65 and Smad2/3 in platelet-exposed cancer cells but did not detect a significant increase in phosphorylation of STAT1/3." (PMID 35626102, 2022). "In this study, we have shown that SMAD2 and SMAD3 exert distinct effects on cancer cell invasion." (PMID 35681731, 2022). "We demonstrate that the selective activation of SMAD3 signaling in hypoxia occurs in a wide variety of cancers and that SMAD2 and SMAD3 exert dichotomous roles in cell invasion, in which SMAD3 drives the invasive properties of cancer cells in vitro and in vivo." (PMID 35681731, 2022). "Further investigations are required to determine whether SMAD4-positive cancer cells, in which SMAD4 cytostatic and pro-apoptotic functions are active, also use SMAD2 and 3 as oncogenic factors." (PMID 36207615, 2022). "Moreover, focal CNA amplifications encompassed genomic peaks that harbored canonical cancer genes including those found at HPV-integrated hotspots (MYC, MYCN, MYCL, SOX2, NR4A2, and ANKRD12), and others (CCNE1, SMAD2, BCL2L1, and GNAS)." (PMID 36216793, 2022). "More studies in recent years have reported that TGF-β mediated Smad3 rather than Smad2 played a crucial role in cancer." (PMID 33757572, 2021). "However, later-stage cancers can become desensitized to the anti-cancer effects of SMAD4 and the SMAD2/3/4 complex." (PMID 34572031, 2021). "The TGF-β/Smad-2/Snail pathway is a master regulation mechanism of EMT induction, and has a recognized relevance in cell differentiation, guiding the metastatic state in a broad number of cancer types." (PMID 34452195, 2021). "Specifically, researchers found that these miRNAs inactivated the TGF- β signaling pathway (an oncogenic pathway in later cancer stages) via targeting several important factors, including SMAD2, SMAD4, and TGFBR1 (for miR-582-3p); and SMAD2, TGFBR1, as well as TGFBR2 (for miR-582-5p)." (PMID 35011442, 2021). "Binding motifs for many essential TFs, such as RXRA, NFE2L2, ESRRA, IRF2, RELA, ESRRA, SOX2, and SMAD2/3, key TFs that mediate TGFβ signaling in epithelial-mesenchymal transition (EMT) and cancer metastasis, were enriched in common gained or LNC-specific gained enhancers, with some overlapping TFs." (PMID 34294701, 2021). "Contrarily, several other studies revealed that SMAD2 suppressed EMT and cancer metastasis." (PMID 34048444, 2021). "It has been reported that inhibitors that reduce SMAD2 and SMAD3 by interrupting the TGF-β signaling pathway could help treat and prevent human cancers, including TNBC." (PMID 33916931, 2021). "We find that, in cancer cells of various origins, acidosis-induced TGF-β2 activation promotes both partial epithelial-to-mesenchymal transition (EMT) and fatty acid metabolism, the latter supporting Smad2 acetylation." (PMID 31974393, 2020). "TGF-β, one role in the pathogenesis of carcinoma, could regulate VEGF release in an ALK-5-dependent manner by SMAD2/3 versus SMAD1/5/8 signalling." (PMID 32308722, 2020). "Consequently, miR-148a blocked the expression/activation of SMAD2 (via targeting the SMAD2-3′-UTR) and thus restored epithelial characteristics, adhesive abilities, and cancer stem cell-like properties." (PMID 31323834, 2019). "Studies that have shown different functional roles of Smad2 and Smad3 in cancer cells never compared the expression of Smad2 and Smad3 at protein level in cancer cells versus normal cells." (PMID 31798766, 2019). "A lot of evidences showed that TGF-β can stimulate EMT in cancer cells and promote distant metastasis by depending or not depending on Smad2/3 signaling pathways." (PMID 30899449, 2019). "TGF-β, secreted by cancer cells and stromal fibroblasts in the cancer microenvironment, is considered as a primary inducer of EMT through inducing SNAIL expression and cooperating with Smad2 and Smad3 and WNT/β-catenin signaling." (PMID 31126310, 2019).
cancer (continued). "Moreover, a number of target genes of miR-155 affect other cancer-related processes, such as cell growth and survival (CCND1 and GAB3), cell adhesion junction (ANKRD6 and SMAD2), proliferation (SOCS1 and STAT3), and apoptosis (TP53BP1)." (PMID 31744065, 2019). "However, recent studies in cancer, pituitary, and ovarian cells have demonstrated BMP-induced activation of SMAD2/3 signaling via several mechanisms." (PMID 29416020, 2018). "Besides TGFβ1/Smad2/3 cascade, there are also Smad-independent pathways involved into TGFβ1-induced EMT of cancer, such as MAPKs and Akt." (PMID 30174709, 2018). "Immunostaining of serial sections from patients showed that cytoplasmic SIK expression in the carcinoma compartment correlated with the expression of phosphorylated Smad2 levels and with complete absence of Par3." (PMID 29464029, 2018). "Down regulation of NRP1 in KRASmt cells decreased the phosphorylation of SMAD2, but there was no change in SMAD2 phosphorylation in KRASwt cancer cells upon NRP1 knockdown." (PMID 29018205, 2017). "Mucin 1 (MUC1) and WNT1 inducible signaling pathway protein 1 (WISP1) have been reported to inhibit E-cadherin-mediated cell-cell adhesion, induce the expression of transcription factors (Snail, N-cadherin, ZEB1 and Smad2), and in turn activate EMT in cancer cells." (PMID 28099903, 2017). "In addition, the five genes (JUN, PRKACA, SMAD2, ESR1, and BCL3) shared by the OV and multi-NCA biomarkers form a small network module and are recognized as cancer-related genes." (PMID 26202601, 2015). "It has been shown that inhibitors that decrease levels of Smad2 and Smad3 through interruption of TGF-β signaling could be valuable tools for treatment of human cancers such as CRC, glioblastoma and breast cancer." (PMID 25980495, 2015). "Smad2 regulates EMT and promotes cancer cell invasion, therefore we reasoned that hsa-miR-140-5p may have an impact on CRC invasion." (PMID 25980495, 2015). "Here, we have used a network-based exploration approach to identify a multi-cancer gene expression biomarker highly connected by ESR1, PRKACA, LRP1, JUN and SMAD2 that can be predictive of clinical outcome in 12 types of cancer from The Cancer Genome Atlas (TCGA) repository." (PMID 26202601, 2015). "Compared to BRAFwt/MSS cancers, BRAFmut/MSS cancers showed significantly more frequent focal deletions at 18q (11/33, 33% Vs 1/18, 6%; p = 0.04) predominantly encompassing 18q21.2 which includes the SMAD2 gene locus." (PMID 24651849, 2014). "The HRG-β1-induced expressions of Snail, vimentin, and fibronectin, and nuclear colocalization of phospho-Smad2 and Snail were inhibited by pretreatment with a PI3k inhibitor, LY294002, or two phospho-Smad2 inhibitors, PD169316 or SB203580 and cancer cell migration by HRG-β1 was inhibited." (PMID 23937725, 2013). "Overall, these results suggest that cytokines production principally depends on the direct interaction between cancer cells and PBMCs, and TGF-β/Smad2/3 signaling might be promoted during this process." (PMID 23342108, 2013). "However, relatively few studies on the roles of Smad2 and Smad3 in TGF-β signalling have been performed in human epithelial cells from which most cancers arise." (PMID 21624123, 2011). "Furthermore, the localisation of active TGF-β1 in these cancers was shown by immunohistochemical staining for active TGF-β1 and its signalling molecule p-smad-2." (PMID 17637685, 2007). "Moreover, several TFs play known roles in cancers, such as ASCL1, NCOR1, SMAD2, and SMAD4." (PMID 39716176, 2024).
cancer (continued). "In addition, dietary intake of creatine or GATM-mediated synthesis of creatine activated SMAD2 and phosphorylated SMAD3 through monopolar spindle 1 (MPS1), upregulated the expression of Snail and Slug, enhanced cancer cell metastasis, and shortened the survival of mice." (PMID 38514720, 2024). "These, in turn, can reactivate dormant DTC proliferation, renew CD133+ cancer cells and endocrine resistance by IL-6/Notch signaling through the IL-6 receptor gp130/gp80 and activated STAT3, through VEGF via PI3K/Akt signaling, SMAD2 and 3, and the EGFR and ERK pathways." (PMID 37296983, 2023). "However, WNK1-induced Smad2 phosphorylation at residue Ser-465 interferes with the TGF-β-induced phosphorylation, nuclear translocation and transcriptional activity of Smad2, thereby inhibiting TGF-β signal transduction in cancer cells." (PMID 36123332, 2022). "In cancers, activated TGF-β ligands bind to TGF-β type II receptors and phosphorylate TGF-β type I receptors, which are an essential component of this bipartite transmembrane receptor; then phosphorylated TbRI subsequently phosphorylates intracellular Smad2 and Smad3 (Smad2/3)." (PMID 33495408, 2021). "Furthermore, in carcinoma cells, loss or very low levels of TβR‐V expression do not affect TGF‐β‐stimulated canonical signaling (TβR‐I/TβR‐II/Smad‐2/3/4), as evidenced by TGF‐β‐stimulated expression of PAI‐1 in these cells." (PMID 34485840, 2021). "SMAD2/3 is a downstream mediator of TGFBR1 and the activation of AKT is considered the main downstream signal of IGF-1R, both SMAD2/3 and p-AKT participate in the process of cancer progression by promoting cell growth, anti-apoptotic effects, and cell invasion." (PMID 31035970, 2019). "Because the molecular networks of TGFR, including Smad pathway (Smad2/3) and non-Smad pathway molecules (e.g., Akt and Erk), regulate cancer cell survival and metastasis, we examined whether fucoidan suppresses the activity of Smad and non-Smad pathways." (PMID 25149540, 2014). "Smad2 heterozygous mice (Smad2+/-) do not develop spontaneous cancer in any tissues." (PMID 22204491, 2011). "Thus, the potential effect of CRF on SMAD2 and β-catenin, and subsequently TGF-β and Wnt signaling, may confer a novel mechanism for crosstalk between cancer cells and stress neuropeptides." (PMID 20875132, 2010). "These seemingly contradictory results might be due, at least in part, to the distinct roles of Smad2, Smad3, and Smad4 in TGF-β signaling in the changing signaling context of cancer progression, resulting in altered target gene expression and ultimately different biological effects." (PMID 16438724, 2006). "As the TGF-β signaling pathway is known to regulate various cellular processes in cancer, including cell growth, cell differentiation, and apoptosis, we thus hypothesized that ACSL4 contributed to OS cell progression by regulating TGF‐β/Smad2 signaling pathway." (PMID 38564125, 2025). "The majority of the 11 p-Smad2/3 downregulated genes we identified here have not been previously linked with TGF-β/Smad2/3 signaling, with the exception of Vim, which is regulated by the TGF-β pathway during the EMT transition of many cell types, including pancreatic and gastric cancer." (PMID 23390484, 2013). "Furthermore, in rat prostatic epithelial cells, Smad2 was shown to be critical for the proapoptotic effect of TGFβ in a premalignant basal cell line (NRP152), while Smad3 mediated the apoptotic response in a malignant luminal carcinoma cell line (NRP154) derived from the same rat prostate." (PMID 20942910, 2010). "While there are no previous reports connecting EMT and quercetin in cancer, quercetin prevented EMT by regulating the Smad2/3 phosphorylation pathway in retinal epithelial cells." (PMID 32492961, 2020).
cancer (continued). "In contrast to previous studies in cancer and pituitary gonadotrope cells, our study in trophoblast cells is the first to implicate ALK2 in BMP2-induced non-canonical SMAD2/3 signaling." (PMID 29416020, 2018). "Finally, the involvement of AKT, SMAD2, SAPK/JNK, survivin, and protein stability, evidenced in this study, could converge in ROS-inducing pathways (e.g., Nuclear factor erythroid-derived 2, NRF2) to increase NGB levels and, ultimately, to cancer cell survival." (PMID 27149623, 2016). "Further data showed that parallel treatment of cancer cells with TGF-β1 and asporin peptide, without prior pre-incubation, failed to inhibit SMAD2 phosphorylation." (PMID 26327350, 2015). "Both phosphorylation of Smad2 and induction of SMAD7 by TGF-β were observed in TβRII-expressing cancer cells, but not in control SCLC cells that expressed green fluorescent protein (GFP) alone (H82-GFP cells and H345-GFP cells)." (PMID 27462425, 2015). "Copy number losses of CRK (P = 0.07), SMAD2 (P = 0.09), FHIT (P = 0.68), and NFATC1 (P = 0.11) genes did not vary significantly between diffuse-type cancers and intestinal-type cancers." (PMID 26360582, 2015).
infection (36 papers, 2008 to 2025). The state of being infected such as from the introduction of a foreign agent such as serum, vaccine, antigenic substance or organism. "Infection with Ad-GCH1 or the addition of BH4 significantly decreased the luciferase activity of the Smad2/3-responsive reporter following radiation." (PMID 38689083, 2024). "The elevated serum TGF-β concentration and p-SMAD2 were further confirmed in Ang II–infused Apoe–/– mice by Lenti-Slc44A2 infection." (PMID 38916960, 2024). "Greater numbers and percentages of cells from the brains of IL10-/- mice were positive for phospho-SMAD2/3 on day 3 after NSV infection compared to WT mice." (PMID 36016413, 2022). "As expected, infection with lentivirus-packaged oe-SMAD2 was noted to augment the expression of SMAD2." (PMID 35379779, 2022). "ALK4 activation by activin A induced mainly (SWAT) or exclusively (EWAT) phosphorylation of Smad2, which was abrogated by infection with CRE-expressing adenovirus." (PMID 36403856, 2022). "We next evaluated the effects of decreased Smad2 and/or Smad3 expression at day 7 after lentiviral shRNA vector infection." (PMID 34691193, 2021). "In contrast to activin, which robustly increased SMAD2 phosphorylation, infection with Toxoplasma was unable to stimulate phosphorylation." (PMID 30891432, 2019). "Consistent with the observed mRNA expression changes, the expression of Smad2/3 was upregulated in immune mice and downregulated in P17-injected mice at 12 and 18 h post-infection." (PMID 30116243, 2018). "In order to dynamically monitor TGFβ signaling activities during embryonic stem cell (ESCs) maintenance and differentiation, we expressed GFP-tagged Smad2 and Smad3 in human ESCs through lentiviral infection." (PMID 26905010, 2016). "In contrast, infection with the ΔvCyclin mutant virus restored SMAD2 protein levels similar to that seen in uninfected iSLK cells." (PMID 26545119, 2015). "Infection of TIVE cells with the ΔvFLIP/ΔvCyc mutant fully restored the SMAD2 expression to levels observed in uninfected TIVE cells." (PMID 26545119, 2015). "Infection of iSLK cells with the ΔvFLIP mutant resulted in a detectable but significantly lower expression level of SMAD2." (PMID 26545119, 2015). "Both Smad2 and Smad3 are significantly phosphorylated in the ceca from Salmonella-infected chickens at 4 days post-infection." (PMID 26664962, 2015). "In primary infection, the SMAD protein Smad2 was found to interact with Acvr1b; whereas in secondary infection, Smad2, Smad3, and Smad7 were found to interacted with Acvr1b." (PMID 25341656, 2014). "To begin testing this hypothesis, we monitored changes in the phosphorylation status of SMAD2 upon infection." (PMID 41450565, 2025). "Downregulation of the BMP-effector SMAD2 in HL also occurs via Epstein-Barr-virus (EBV)-infection." (PMID 37428779, 2023). "However, quantitative analysis of histological samples of SMAD2-positive hepatic cells significantly increased during the course of infection." (PMID 36355906, 2022). "P.g.-infection induced activation of Smad2, Smad3, and ERK1/2." (PMID 32139740, 2020). "By qPCR analysis of whole‐kidney RNA, Smad2 expression in TC‐treated mice was statistically equivalent to that in vehicle‐treated mice across the course of infection, while Smad3 expression was significantly suppressed in TC‐treated mice at 7 dpi, recovering by 28 dpi." (PMID 32227630, 2020). "However, when TGF-β1 was blocked during C. albicans whole blood infection with a neutralizing antibody, SMAD2/3 phosphorylation was inhibited." (PMID 32393780, 2020). "Infection with wildtype KSHV abolished expression of SMAD2 protein in these endothelial cells." (PMID 26545119, 2015). "Alpha-smooth muscle actin (α-SMA), collagen I, collagen III, TGF-β1, Smad2, Smad3, and Smad4 showed a significant increase in mitochondrial RNA (mRNA) and protein expression compared with the control group at 7 and 9 weeks post-infection (wpi), while an opposite effect on Smad7 was observed." (PMID 36474240, 2022).